SMAD3 (SMAD family member 3)
Diseases named in the same sentence as SMAD3 in open-access papers (continued):
Sharing a sentence is not in itself a finding about the gene and the disease.
osteosarcoma (15 papers, 2015 to 2025). A usually aggressive malignant bone-forming mesenchymal neoplasm, predominantly affecting adolescents and young adults. "In addition, an expression vector carrying mutated or wild-type Smad3 was constructed and transfected into osteosarcoma cells." (PMID 32982740, 2020). "However, this suppressive effect of miR-16-5p on the proliferation of osteosarcoma cells was attenuated in the cells expressing mutated Smad3, wherein miR-16-5p was unable to recognize and bind to the mutated 3′-UTR of Smad3." (PMID 32982740, 2020). "miR-16-5p expression is significantly down-regulated in osteosarcoma and suppresses osteosarcoma progression and invasion by targeting Smad3." (PMID 40764609, 2025). "In summary, these findings demonstrate that hfCas13d‐mediated PLK1 suppression is capable of substantially attenuating the in vivo tumour growth of osteosarcoma xenografts, potentially through the regulation of Smad3 activity." (PMID 38780513, 2024). "miR-16-5p has been to be down-regulated in osteosarcoma cell lines compared with control cells, parallel with up-regulation of Smad3." (PMID 36348403, 2022). "Since the phosphorylation of Smad2 and Smad3 plays a pivotal role in TGFβ signaling, we tested the phosphorylation level of Smad2 and Smad3 after treating osteosarcoma cells with gradient concentrations of AMTB." (PMID 35361751, 2022). "Previous studies have also shown that inhibition of CDK2/9 in triple-negative BC cells and CDK9 inhibition in osteosarcoma cells decreased migration by preventing phosphorylation of CDK-mediated Smad3 and RNA POL-ll in triple-negative BC33,34." (PMID 33723248, 2021). "We evaluated Smad3 expression in osteosarcoma cells transfected with miR-16-5p mimic, miR-NC, miR-16-5p inhibitor, or NC inhibitor with western blotting." (PMID 32982740, 2020). "In our study, miR-16-5p can down-regulate Smad3 to promote the anti-cancer effect of cisplatin on osteosarcoma." (PMID 32982740, 2020). "Incubation of osteosarcoma cells with 20 μg/ml of cisplatin for 48 h resulted in the reduction in the level of miR-16-5p with a simultaneous increase in Smad3 expression." (PMID 32982740, 2020). "The results showed that miR-16-5p expression was downregulated in osteosarcoma tissues and cells as compared with adjacent counterparts, while Smad3 was overexpressed in osteosarcoma cells." (PMID 32982740, 2020). "A recent study has found that the overexpression of p-Smad2, p-Smad3, and Smad4 increased caspase 3 and caspase 9 activation in osteosarcoma cells." (PMID 32126993, 2020). "Upregulation in miR-16-5p expression significantly inhibits the proliferation, migration, and invasion of osteosarcoma cells by silencing mothers against decapentaplegic homolog 3 (Smad3) expression." (PMID 32982740, 2020). "Taken together, miR-16-5p suppressed the proliferation, migration, and invasion of osteosarcoma cells by regulating the expression of Smad3." (PMID 32982740, 2020). "Taken together, we demonstrate that miR-16-5p expression is downregulated in osteosarcoma and that overexpression of miR-16-5p inhibits the proliferation, migration, and invasion of osteosarcoma cells by targeting Smad3." (PMID 32982740, 2020). "We detected the expression of Smad3 in multiple human osteosarcoma cell lines and a human osteoblast cell line." (PMID 32982740, 2020). "The overexpression of miR-16-5p resulted in the suppression of Smad3 expression in osteosarcoma cells and this suppressive effect was attenuated following downregulation of miR-16-5p expression." (PMID 32982740, 2020). "Transcription factor consensus sequences for interferon‐gamma activated site (GAS) and SMAD3/4 competed‐out binding of radiolabeled probe to the CpG8‐9 region in osteosarcoma cell line extract." (PMID 28419547, 2017).
osteosarcoma (continued). "Here, we demonstrated that the ability of halofuginone to inhibit the TGF-β/Smad3 cascade in osteosarcoma reduces the expression and activity of MMP-2, a protein highly implicated in the migration and invasion processes." (PMID 26015407, 2015). "Notably, cells harboring Smad3 mutation have not responded to miR-16-5p over-expression, indicating that miR-16-5p suppresses invasive properties of osteosarcoma cells through suppressing expression of Smad3." (PMID 36348403, 2022). "Finally, we added TGFβ (5 ng/ml) to AMTB-treated osteosarcoma cells and observed that the phosphorylation level of Smad2 and Smad3 was rescued to basal level." (PMID 35361751, 2022). "Furthermore, osteosarcoma cells were incubated with cisplatin for 48 h, and the expression of Smad3 mRNA and miR-16-5p was detected with RT-PCR." (PMID 32982740, 2020). "Immunoblot assay revealed the increase in the expression of Smad3 in osteosarcoma cell lines." (PMID 32982740, 2020). "Smad3 was overexpressed in the osteosarcoma tissue as compared with the adjacent tissue." (PMID 32982740, 2020). "This study firstly investigated that miR-16-5p inhibited the proliferation, migration, and invasion of osteosarcoma via suppressing the expression of Smad3, meaning that miR-16-5p may be regarded as a potential target in the treatment of osteosarcoma." (PMID 32982740, 2020). "The expression of Smad3 in human osteosarcoma specimens was detected with immunohistochemistry." (PMID 32982740, 2020). "Therefore, miR-16-5p inhibits the growth and invasion of osteosarcoma by targeting Smad3." (PMID 32982740, 2020). "Therefore, we hypothesized that miR-16-5p downregulates Smad3 expression in osteosarcoma cells, thereby inhibiting their proliferation and enhancing their sensitivity to chemotherapy." (PMID 32982740, 2020). "Inhibiting SRC activated by TGF-β1 impaired the activation of ERK, Smad2, and Smad3, as well as Smad nuclear translocation, which, in turn, inhibited the induction of CTGF in rat osteosarcoma osteoblast-like cells." (PMID 38167009, 2024). "Because we recently demonstrated that TGF-β/Smad cascade plays a crucial role in osteosarcoma metastatic progression, we investigated the effect of halofuginone, identified as an inhibitor of the TGF-β/Smad3 cascade, on osteosarcoma progression." (PMID 26015407, 2015). "Concerning osteosarcoma, we recently demonstrated that TGF-β1 levels are higher in the serum of patients compared to healthy donors and that TGF-β/Smad3 signaling pathway is activated in human biopsies." (PMID 26015407, 2015). "Interestingly, PLK1 silencing markedly increased Smad2 and Smad3 phosphorylation in both MG‐63 and U2OS osteosarcoma cell lines." (PMID 38780513, 2024). "Meanwhile, the levels of TGFB2, p-Smad2, p-Smad3, and BMP-6 showed a reverse trend after the SRI-011381 application, suggesting that PNO1 could influence the progression of osteosarcoma cells via the TGF-β signaling pathway." (PMID 38071381, 2023). "Collectively, these finding suggested that the interaction between osteosarcoma cells and platelets, via thrombin and TGF-β, results in a continuous cycle, and that anti-TGF-β or anti-Smad3 therapy could be a promising tool for disease treatment." (PMID 32982740, 2020). "It was revealed that osteosarcoma cells could release TGF-β, which can be suppressed by inhibitors of TGF-β type I receptor and knockdown of Smad3." (PMID 32982740, 2020).
endometriosis (14 papers, 2014 to 2025). The growth of functional endometrial tissue in anatomic sites outside the uterine body. "SMAD3, on the other hand, has been shown to be upregulated in patients with endometriosis suggesting that regulatory variants in this gene may influence the pathology and progression of the disease." (PMID 40863222, 2025). "The endometriosis risk allele G rs440837 reduces affinity for the TF Hoxa9 (the difference in the “LODscores” parameter of the G and A alleles was −1.7) and increases sensitivity to TFs Hlx1 and Smad3 (differences in the “LODscores” of the G and A alleles are 1.5 and 7.5, respectively)." (PMID 41373783, 2025). "In our work, we also investigated the expression of SMAD3 mRNA in the endometrium of women with endometriosis." (PMID 36768775, 2023). "Western blot analysis showed that the protein expression of Smad2 and Smad3 was increased in THP-1 cell-derived macrophages treated with serum from endometriosis patients in the presence of LPS, as compared with that in control cells." (PMID 30276219, 2018). "More importantly, disturbances in intracellular signaling pathways related to the pathological expression of EMT mesenchymal biomarkers (TGF-β1, SMAD3 and ILK) may have clinical significance in the diagnostic and therapeutic aspects of endometriosis." (PMID 36768775, 2023). "Moreover, there is evidence that miR-21 inhibits the translation of TGFβ-1 mRNA in various diseases, including endometriosis, and the post-transcriptional regulation of miR-21 via SMAD3 plays a key role in its upregulation and the development of fibrosis." (PMID 36768775, 2023). "Upregulation of Smad2/Smad3 in macrophages upon exposure to eutopic and ectopic endometrial homogenates as well as serum of women with endometriosis was observed, and blockage of Smad2/Smad3 with their inhibitor SB431542 could reverse the macrophage polarization from M1 to M2." (PMID 30276219, 2018). "In the case of SMAD3, the mean RQ was 0.318956 in the ECE and 0.902240 in the EUE of patients with endometriosis, and 0.543976 in the endometrium of the control group." (PMID 36768775, 2023). "Endometriosis patients manifested higher TGF-β1, SMAD3, and ILK expression levels in the eutopic endometrium and a decreased expression level in the ectopic lesions in relation to control tissue." (PMID 36768775, 2023). "Preincubation with the Smad2/Smad3 inhibitor SB431542 resulted in a decrease in the percentage of CD163+ cells, which was only observed in macrophages treated with serum from endometriosis patients." (PMID 30276219, 2018). "The additional Mann–Whitney U test also showed statistically significantly lower expression of TGF-ß1, SMAD3 and ILK in ectopic lesions compared to matched eutopic endometrium in women with endometriosis (p = 0.023471, p = 0.026057 and p = 0.006639; respectively)." (PMID 36768775, 2023). "Analyzing the expression of SMAD3 mRNA in the eutopic tissue of women with and without endometriosis, we also did not demonstrate statistically significant differences between the studied groups." (PMID 36768775, 2023). "Additionally, the purpose of the study was to analyze the correlation between TGF-β1, SMAD3, ILK and miR-21 expression levels and the clinical features and biochemical parameters of patients with endometriosis." (PMID 36768775, 2023). "However, because pSMAD3 levels were similar in patients with and without endometriosis, the authors postulate that the phosphorylation of SMAD3 is precisely regulated by specific mechanisms, mainly by activating TGFβ/activin receptor ligands." (PMID 36768775, 2023). "Therefore, in the future, we plan to analyze cell lines regarding the effect of miR-21, TGF-β1, SMAD3, and ILK expression levels on the biological functions of endometrial cells, which will provide innovative theoretical references in terms of molecular targets for endometriosis treatments." (PMID 36768775, 2023).
endometriosis (continued). "Nevertheless, as SMAD3 is one of the most important intracellular mediators in TGF-β signaling, based on our observations, it can be hypothesized that in the case of a disorder of its expression in endometriosis, the functionality of all proteins in the TGF-β superfamily can be changed." (PMID 36768775, 2023). "The expression levels of the TGF-ß1, SMAD3, ILK and miR-21 genes were assessed in PBMCs obtained from patients with endometriosis and in PBMCs from patients without endometriosis, who constituted the control group (C2)." (PMID 36768775, 2023). "To the best of our knowledge, we were the first to assess changes in the level of expression of TGF-β1, SMAD3, ILK and miR-21 in the PBMC of patients with and without endometriosis." (PMID 36768775, 2023). "The eutopic endometrium of women with endometriosis showed higher expression of the mRNA TGF-β1, SMAD3 and ILK, and the level of miR-21 did not change compared to the endometrium of healthy participants." (PMID 36768775, 2023).
glomerulosclerosis (14 papers, 2014 to 2025). A hardening of the kidney glomerulus caused by scarring of the blood vessels. "Surprisingly, selectively interfering with SMAD3 signaling can attenuate glomerulosclerosis; however, this has shown minimal effects in preventing proteinuria in experimental DN." (PMID 40558517, 2025). "The PPARγ agonist rosiglitazone has been shown to inhibit mesangial cell proliferation, serine protease activity, and TGFβ expression, while activating the TGFβ-Smad3 signaling pathway, thereby preventing the progression of glomerular sclerosis." (PMID 40442892, 2025). "Inhibition of TGF-β1 or ablation of SMAD3 (SMAD−/−) showed promising protection from glomerulosclerosis and renal dysfunction." (PMID 33795655, 2021). "We observed that db/db mice showed severe glomerulosclerosis and the increase in Col4 expression and Smad3 activation." (PMID 31150422, 2019). "In a podocyte ablation model, HIF‐1α has been shown to induce glomerulosclerosis through interaction with Smad3 (Baumann, Hayashida, Liang, & Schnaper, 2016)." (PMID 30614190, 2019). "In addition, PECs displayed reduced SMAD3 phosphorylation and glomerulosclerosis, as visualized by less prominent smooth muscle actin (SMA) staining." (PMID 41028563, 2025). "Among its components, Lei Gong Teng polyglucoside has been shown to alleviate glomerulosclerosis in rats with adriamycin nephropathy by regulating the expression of TGF-β1, Smad3, p-Smad2/3, and Smad7." (PMID 39687302, 2024). "In addition, the well-known TGFβ/SMAD3 fibrotic signal was also found to be mediated by PI3K/AKT signaling, which further establishes the importance of this pathway in HG mediated glomerulosclerosis." (PMID 25474550, 2014).
emphysema (13 papers, 2008 to 2025). "Smad3-deficient mice show progressive alveolar destruction resembling emphysema while they are protected from bleomycin-induced lung fibrosis." (PMID 30127261, 2018). "Smad3-deficient mice show impaired alveolarization and centrilobular emphysema, similar to the effect of TGFβR-II abrogation in lung epithelial cells." (PMID 30127261, 2018). "Itgb6-null mice develop age-related emphysema, similar to the effects of Smad3 deficiency or TGFβR-II abrogation in lung epithelial cells." (PMID 30127261, 2018). "This is compatible with the observation that Smad3 deficiency in mouse knock-out models results in abnormal lung alveolarization resembling emphysema." (PMID 19087346, 2008). "TGF-β1/Smad3 signaling pathway has critical functional roles in the development of both emphysema and fibrosis in the lung." (PMID 26753996, 2016). "Retarded lung alveolarization and subsequent emphysema in Smad3 knockout mice, on the other hand, suggests a role for the TGF-β/Smad3 pathway in postnatal lung growth and emphysema prevention." (PMID 19580641, 2009). "SMAD3‐knockout mice developed impairment in alveolarization and centrilobular emphysema." (PMID 39083441, 2025). "Previously, the Smad3 signaling pathway has been shown to be involved in emphysema." (PMID 39456887, 2024). "For instance, Smad3 could generally amplify TGF-β signal, and conditional knockout of the Smad3 gene can cause alveolar expansion in diseases such as bronchopulmonary dysplasia (BPD) or emphysema." (PMID 30988675, 2019). "Although knocking down basal Smad3 expression might be beneficial for blocking TGF-β1 induced FMD, loss of Smad3 has been reported to correlate with enlargement of airspaces and development of emphysema." (PMID 24762191, 2014). "Our data demonstrated that OVA/S mice enhance emphysema and expressions of TGF-β and Smad proteins in vivo and co-localization of mast cells and Smad3 protein in lung tissues." (PMID 21496353, 2011).
Hypertension (13 papers, 2013 to 2023). The presence of chronic increased pressure in the systemic arterial system. "To further explore the effects of phenylacetamide on hypertension and cardiac function, we examined the expression of Smad3 protein." (PMID 32631115, 2020). "In conclusion, AKBA is able to attenuate oxidative stress and profibrotic mechanisms, and improve vascular remodeling in hypertension through TGF-β1/Smad3 pathway." (PMID 28009003, 2016). "Furthermore, we initiated an angiotensin receptor-blocker, which generally would not have been considered in the absence of hypertension if the patient was not suspected to have SMAD3-associated aortopathy." (PMID 36926042, 2023). "Therefore, TGF-β1/Smad3 signaling pathway may play a crucial role in kidney injury in SS hypertension during chronic treatment with AEA." (PMID 35413977, 2022). "Overall, our study shows that prolonged treatment with a high dose of AEA contributes to the aggravation of SS hypertension and a consequent kidney injury, which in turn activates Nrf2-modulated TGF-β1/Smad3 pro-fibrotic signaling." (PMID 35413977, 2022). "Furthermore, we also detected that Smad3 KO‐db/db mice, but not Smad3 WT‐db/db and Smad3+/− db/db mice, were protected from the development of hypertension by maintaining a normal range of blood pressure." (PMID 33733577, 2021).
Alzheimer disease (12 papers, 2010 to 2025). A progressive, neurodegenerative disease characterized by loss of function and death of nerve cells in several areas of the brain leading to loss of cognitive function such as memory and language. "For example, brains affected by Alzheimer disease are associated with decreased levels of SMAD3, while SMAD3 phosphorylation (i.e., activity) is reduced in proximal tubular cells stimulated with IL-1β and in cardiac fibroblasts treated with LPS." (PMID 30363688, 2018). "Blood SMAD3 levels are associated with Alzheimer’s disease-related neuroimaging outcomes." (PMID 38902234, 2024). "LEFTY2’s ability to inhibit TGF-β-induced Smad3 phosphorylation offers a potential strategy to modulate the effects of TGF-β in Alzheimer’s disease." (PMID 40244244, 2025). "Of the vascular molecular targets predicted to interact with astrocytic ligands, SMAD3, upregulated in Alzheimer’s disease pericytes, has the highest number of ligands including VEGFA, downregulated in Alzheimer’s disease astrocytes." (PMID 38902234, 2024). "In mice exposed to CCl4, Ad-Hep infection notably inhibited Smad3 phosphorylation with minimal inhibition of Smad2 phosphorylation." (PMID 28004654, 2016). "For instance, in a recent study, investigators sought to quell inflammation in the brain by manipulation of TGFβ and SMAD3 in immune cells as a new method to prevent Alzheimer's disease." (PMID 20436665, 2010). "Here, we detect vast transcriptome changes in Alzheimer’s disease at the gliovascular-unit, prioritize perturbed pericytic SMAD3-astrocytic VEGFA interactions, and validate these in cross-species models to provide a molecular mechanism of blood-brain-barrier disintegrity in Alzheimer’s disease." (PMID 38902234, 2024). "The majority of vascular transcriptional changes occur in pericytes, with SMAD3 upregulated in Alzheimer’s disease pericytes having the highest number of ligands including VEGFA, which is downregulated in Alzheimer’s disease astrocytes." (PMID 41465272, 2025). "Furthermore, in the context of neurodegenerative pathology such as Alzheimer’s disease, PAI-1 protects mature neurons from excitotoxicity via the TGF-β1/Smad3 and TrkA/c-Jun pathways, and modulates aberrant migration in fragile X syndrome models." (PMID 41515965, 2025). "In Alzheimer’s disease (AD) models, PAI-1 confers neuroprotection against NMDA receptor-mediated excitotoxicity via the TGF-β1/Smad3 signaling pathway, whereas astrocyte-derived PAI-1 enhances PC-12 cell survival through the TrkA receptor and c-Jun/AP-1 pathway activation." (PMID 41515965, 2025).